MTOR (mechanistic target of rapamycin kinase)
Diseases named in the same sentence as MTOR in open-access papers (continued):
Sharing a sentence is not in itself a finding about the gene and the disease.
kidney transplant (41 papers, 2011 to 2025). A surgical procedure in which one or both kidneys from a donor are implanted into a recipient. "In a study on cultured cells from 24 lung NETs, mostly TCs, higher expression of mTOR and p-mTOR (Ser2448) was associated to response to everolimus in vitro." (PMID 29509701, 2018). "The mTOR inhibitor everolimus is licensed for the prophylaxis of allograft rejection in combination with reduced-exposure CNI in adult kidney transplant patients at low or moderate immunologic risk and in liver transplant recipients." (PMID 27807479, 2016). "In conclusion, variants in genes of mTOR and calcineurin pathways are associated with long-term impaired renal function, increased risk of acute rejection, and, individually, with adverse events in Brazilian kidney transplant recipients." (PMID 30487748, 2018). "Thus, Sag appears to act as an oncogenic gene cooperating with Pten-loss to promote prostate tumorigenesis by activating the PI3K/AKT/mTOR signaling pathway." (PMID 27955654, 2016). "Pulmonary functional tests before (T0) and after (T6) 6 months follow up of immunosuppressive therapy with MMF/MYF or mTOR-i in kidney transplant recipients enrolled in the study." (PMID 40568197, 2025). "Targeting mTOR inhibition presents a promising approach to addressing the challenges of treating human lung cancer." (PMID 40287470, 2025). "Hearing problems in 46 kidney transplant patients [eGFR ≥ 60 ml/min/1.73 m2 (30 Tacrolimus, 16 mTOR inhibitor users)], 23 hemodialysis patients, and 20 healthy controls were evaluated with a questionnaire and high-frequency audiometry." (PMID 35497888, 2022). "The essential role of mTORC1 in lipogenesis is underlined by the observation that SREBP1 activation is prevented by the mTOR inhibitor rapamycin and that mTOR-deficient mice are protected from HFD-induced liver steatosis." (PMID 32235829, 2020). "Further investigation identified the GSKα/β pathway as a central regulator of this adaptive glutamine metabolism that enables lung SCC tumors to escape the effects of mTOR inhibition by upregulating glutaminase expression." (PMID 32083006, 2020). "In this section, we will discuss the regulatory role of mTOR signaling on inflammatory cells and humoral factors in liver IR injury." (PMID 31827701, 2019). "In this review, we focused on the impact of mTOR signaling on inflammatory response and autophagy to discuss the beneficial effect of mTOR signaling on liver IR injury." (PMID 31827701, 2019). "Since the indispensable role of mTOR signaling on autophagy, numerous researches focused on mTOR signaling for regulating autophagy to protect against liver IR injury." (PMID 31827701, 2019). "Bortezomib, melatonin, geniposide, NaHS, and agomir-miR-494 administration attenuated liver IR injury through activating mTOR signaling." (PMID 31827701, 2019). "In a word, the impact of mTOR signaling on the inflammatory response and autophagy provides an attractive therapeutic target for liver IR injury." (PMID 31827701, 2019). "Researches have shown that melatonin and microRNA-101 attenuated liver IR injury by suppressing autophagy through activating mTOR signaling." (PMID 31827701, 2019). "Pharmacological inhibition of mTOR by chronic dosing with free rapamycin is used to prevent kidney transplant rejection." (PMID 29552007, 2018). "Reduction of immunosuppressive intensity is the first step in management, but the Kidney Disease Improving Global Outcomes (KDIGO) recommendations suggest that treatment with an mTOR inhibitor also be started." (PMID 27807479, 2016). "Additionally, the mTOR inhibitors sirolimus and tacrolimus are commonly used immunosuppressive medication to prevent post-kidney transplant rejection." (PMID 40510153, 2025). "In a prospective observational study of 993 prevalent kidney transplant recipients without a history of malignancy, long-term exposure to mTOR inhibitors was associated with significantly increased mortality." (PMID 39124572, 2024).
kidney transplant (continued). "Moreover, mTOR inhibitors even improve the T cell-stimulating ability of mDCs in kidney transplant recipients." (PMID 37887285, 2023). "It will also be important to determine whether blockade of both mTOR and MyD88 completely prevents development liver inflammation." (PMID 34630435, 2021). "Mammalian target of rapamycin (mTOR) is a critical regulator of cell growth and metabolism that senses and integrates various signals under physiological and pathological conditions, playing critical roles in regulating liver IR injury." (PMID 31827701, 2019). "Additionally, mTOR-deficient mice showed greater expression levels of inflammation-related genes such as MCP-1, TNF-α, and IL-6 than wild-type (WT) mice after liver IR via negatively modulating NF-κB." (PMID 31827701, 2019). "In summary, the MC-LR could aggravate the HFD-induced obese mice liver lipid metabolism disorder by activating the PI3K/AKT/mTOR/SREBP1 signaling pathway to hepatocytes, increasing the SREBP1-c-regulated key enzymes for lipid synthesis, and blocking fatty acid β-oxidation." (PMID 36548730, 2022). "However, the role and mechanism of mTOR signaling on regulating CD4+ T lymphocytes in liver IR injury remain unclear; further investigations are needed to reveal." (PMID 31827701, 2019). "Blockade of mTOR signaling by rapamycin in CBL-/- CBL-B-/- mice concomitantly reduces the number of liver CD103+ cDC1s and the incidence of liver inflammation and fibrosis." (PMID 34630435, 2021). "Upregulation of mTOR and its downstream target gene p70S6K, which in turn activates HIF-1α, exacerbates ischemia/reperfusion-induced liver inflammation." (PMID 32719658, 2020). "To ascertain whether the role of p‐Csp in mitigating prostatitis is through activating autophagy by the modulation of the AMPK/MTOR signaling pathway, we detected the expression of AMPK/MTOR by western blot analysis." (PMID 40552335, 2025). "Based on these findings, a regimen containing once-daily tacrolimus and an mTOR inhibitor with or without corticosteroid is a viable immunosuppressive regimen post-kidney transplant." (PMID 37746361, 2023). "Furthermore, it has been reported that the NF-ĸB/mTOR and PI3/Akt signaling pathways mediated apoptosis induction in the WA-treated breast TNBC cells." (PMID 36676955, 2022). "The study aimed to explore whether the mechanism of rapamycin inhibits the activation of NLRP3 inflammatory bodies by regulating mTOR, to explore the therapy of OSA-induced kidney injury." (PMID 35184679, 2022).
acute kidney injury (40 papers, 2014 to 2025). Sudden and sustained deterioration of the kidney function characterized by decreased glomerular filtration rate, increased serum creatinine or oliguria. "This leads mTOR to react in starvation mode, which stops cell differentiation, leading to proximal tubule loss, and ultimately renal failure." (PMID 40546328, 2025). "Silencing PTEN can stimulate AKT/mTOR signaling, reducing autophagy and oxidative stress levels, which in turn alleviates acute kidney injury in mice." (PMID 40043208, 2025). "In similar studies, the PI3K/Akt/mTOR pathway was related to acute kidney injury triggered by cisplatin and acute lung injury induced by bleomycin." (PMID 38582846, 2024). "Downregulation of the PI3K/AKT/mTOR pathway protects against lipopolysaccharide-induced acute kidney injury by enhancing autophagy." (PMID 35757387, 2021). "Adoptive transfer of rapamycin-treated Tregs ameliorated kidney fibrosis and improved renal functions in mice with acute kidney injury, suggesting an important role of mTOR signaling in regulating Treg functions." (PMID 32708044, 2020). "Further, CaMKIV regulates autophagy through mTOR signaling in lipopolysaccharide-induced inflammation and acute kidney injury." (PMID 32660483, 2020). "In fact, the activation of mTOR seems to be strongly related to many renal diseases, playing an important role in diabetic neuropathy, acute kidney injury, polycystic kidney disease, glomerulopathy, intrarenal inflammation, and interstitial fibrosis." (PMID 28877670, 2017). "Here, we showed that inhibition of mTOR signal enhanced MDSCs' protective effect against acute kidney injury in mice model." (PMID 28333137, 2017). "This may be explained by either their early death due to renal failure that occurs before renal neoplasia can develop or by differences in the degree of mTOR hyperactivation between TFEB overexpressing mice and Six2Cre+Tfap2bfl/fl mice." (PMID 35468900, 2022). "The protective roles of Tregs were regulated by mTOR in the repair of acute kidney injury." (PMID 32708044, 2020). "The number, TLT index, and size of TLTs were significantly reduced by treating ischemic acute kidney injury (AKI) mice with the mTOR inhibitor Torin2." (PMID 40496859, 2025). "Our previous study demonstrated that blocking the mTOR signaling pathways ameliorated acute kidney injury (AKI) by promoting the induction, recruitment, and immunosuppressive activity of MDSCs." (PMID 33897705, 2021). "In acute kidney injury (AKI), the mTOR inhibitor rapamycin protected mouse kidneys from AKI in vivo through the induction and recruitment of MDSCs to suppress an excessive immune response." (PMID 37277776, 2023). "mTOR signaling and adenosine-monophosphate activated-protein kinase (AMPK) are major regulators of autophagy in acute kidney injury (AKI) induced by cisplatin treatment." (PMID 36232665, 2022). "Administration of rapamycin suppressed activation of the mammalian target of rapamycin (mTOR) and activated MDSC during acute kidney injury." (PMID 33868315, 2021). "In the acute kidney injury mouse model, inhibition of mTOR signaling by rapamycin promotes MDSC recruitment and enhances PMN-MDSC development and suppressive function of MDSCs to ameliorate acute kidney injury." (PMID 30057917, 2018). "In this study, we aimed to investigate the role of MDSCs in the protection of acute kidney injury (AKI) and the regulation of mTOR signal on MDSC's protective role in this context." (PMID 28333137, 2017). "Another study addressing the murine MDSC response to acute kidney injury demonstrated that MDSC reduced the injury, and the effect was potentiated by MDSC induction and enhancement of the immunosuppressive activity promoted by mTOR." (PMID 32425928, 2020).
acute kidney injury (continued). "Another recent study found that circ-ZNF609 encodes ZNF609-250aa, a 250-aa novel protein that exacerbates acute kidney injury (AKI) by inhibiting autophagic flow and inducing apoptosis via an AKT/mammalian target of rapamycin (mTOR)-dependent mechanism." (PMID 41181701, 2025). "Furthermore, the results indicate that CaMKIV can regulate autophagy via mechanisms that are independent of mTOR suppression, underscoring its pivotal role in modulating autophagy in the context of LPS-induced acute kidney injury." (PMID 39544947, 2024). "Moreover, mTOR activity is low or absent in the normal kidney but increases markedly after acute kidney injury." (PMID 24853130, 2014).
liver diseases (40 papers, 2014 to 2026). "This study provides mechanistic insight into metabolic and stress-response signaling in AATD and identifies mTOR modulation as a promising therapeutic strategy for AATD-associated liver disease." (PMID 42072628, 2026). "In conclusion, by blocking the PI3K/AKT/mTOR pathway, SchC successfully repaired the autophagy damage in the mouse liver, opening up a new therapeutic avenue for the management of associated liver disorders." (PMID 40582769, 2025). "Alterations in the mTOR signaling pathway have been associated with various human pathologies, notably liver diseases, and have also been correlated with the inhibition of cancer cell growth through suppression of the AKT/PI3K/mTOR axis." (PMID 41516140, 2025). "Depletion of the mTOR pathway in adipocyte exacerbates liver injuries induced by alcohol gavage and affects alcohol-associated liver disease (ALD) through liver-adipose tissue crosstalk." (PMID 38069199, 2023). "To examine if OTULIN deficiency led to mTOR-driven liver disease, we tested if inhibition of mTOR could reduce the pathology in the Otulin∆hep mice." (PMID 32231246, 2020). "Further investigations utilizing animal models of liver cirrhosis-associated portal hypertension will be required to confirm whether and how the mTOR signaling pathway may contribute to liver cirrhosis-associated splenomegaly." (PMID 28535799, 2017). "The gut microbiota and mTOR-signaling pathways have been shown to play an important role in liver diseases." (PMID 37511569, 2023). "In general, the dysregulation of the gut microbiota and mTOR signal will promote the progression of liver diseases, in which autophagy and immune cells are also involved." (PMID 37511569, 2023). "The AMPK/mTOR pathway is a classical pathway related to autophagy, and is widely involved in the pathologies of liver injury and liver disease." (PMID 36766230, 2023). "Excessive apoptosis of hepatocytes is a typical feature of liver disease and is regulated by mammalian targets of the rapamycin (mTOR) signaling pathway." (PMID 36358493, 2022). "The protective effect of puerarin on 2-AAF/ph-induced liver injury is achieved by inhibiting the mTOR signaling pathway, which will provide important ideas for exploring the anti-liver disease target of puerarin." (PMID 36358493, 2022). "PI3K/AKT, AMPK, Ras/Raf/MEK/ERK are just some of the upstream pathways that have been explored in liver diseases through the regulation of mTOR-mediated autophagy." (PMID 34639052, 2021). "Previous studies provided some insights into the regulation mechanisms of GP73 expression via activation of the mammalian target of rapamycin (mTOR) pathway and inflammation-related factors such as Interleukin-6 (IL-6) in liver disease." (PMID 33540642, 2021). "Our findings demonstrate that mTOR activity promotes fibrosis and liver disease in Otulin∆hep mice, but also that mTOR inhibition by rapamycin is insufficient to completely prevent liver pathology in these mice." (PMID 32231246, 2020). "In the next section we will focus on the key role of the AMPK/mTOR/Autophagy signaling pathway in the treatment of various liver diseases." (PMID 31835352, 2019). "Consistently, activation or inhibition of PI3K/Akt/mTOR signaling pathway also played a critical role in many types of liver diseases." (PMID 30283336, 2018). "It is known that excessive hepatocellular apoptosis is a typical characteristic of hepatic disease, and is regulated by the mammalian target of rapamycin (mTOR) signaling pathway." (PMID 30405406, 2018). "Our results hinted that protective effect of Pue on the 2-AAF/PH induced liver injury were realized by inhibiting mTOR signaling pathway, which will provide an inportant idea to explore the target of Pue protected against liver disease." (PMID 30405406, 2018). "Intriguingly, hyperactivity of mTOR pathway was usually found in the process of many hepatic diseases in clinical and experimental cases." (PMID 28638431, 2017).
liver diseases (continued). "So we think that dysregulation of the TSC/mTOR pathway on apoptosis is emerging as a common theme in diverse hepatic diseases; it is hinted that target TSC/mTOR pathway is a feasible therapeutic strategy to treat hepatic diseases." (PMID 28638431, 2017). "Intriguingly, hyperactivity of TSC/mTOR pathway plays a significant role in most of these diseases as hepatic disease." (PMID 28638431, 2017). "We found that P-p70S6K and P-S6 relative to their total protein were elevated in spleens of PHT patients, suggesting mTOR signaling pathway was overactivated, at least in p70S6K/S6 down-stream, in splenomegaly of portal hypertensive patients." (PMID 26734934, 2016). "We also found that splenomegaly developed progressively in a time-dependent manner in rats of both intrahepatic and prehepatic portal hypertension models, which was closely in relevance with progressive activation of mTOR signaling pathway." (PMID 26734934, 2016). "This study provides compelling evidence indicating that mTOR signaling activation pathway plays a key role in the pathogenesis of splenomegaly in both portal hypertensive patients and rats." (PMID 26734934, 2016). "To our knowledge, we for the first time demonstrated that the AKT/mTOR signaling pathway was significantly overactivated and mTORC1 rather than mTORC2 was inhibited by rapamycin in the early phase of cirrhotic portal hypertension in rats." (PMID 24404143, 2014). "This study characterizes the pathogenetic mechanisms leading to cholestatic liver fibrosis and portal hypertension, and focuses on mammalian target of rapamycin (mTOR) pathway as a potential modulator in the early phase of cirrhotic portal hypertension." (PMID 24404143, 2014). "We extensively evaluated the early pathological processes and systematically explored AKT/mTOR signaling pathway in the early phase of cirrhotic portal hypertension." (PMID 24404143, 2014). "Several studies have established a role for mTOR as an attractive target for portal hypertension and antifibrotic therapy." (PMID 24404143, 2014). "In conclusion, this study demonstrated that the activation of AKT/mTOR signaling pathway was clearly involved in the pathophysiological onset of early cirrhotic portal hypertension in rats." (PMID 24404143, 2014). "The AKT/mTOR signaling pathway was markedly activated in the early phase of cirrhotic portal hypertension induced by BDL in rats." (PMID 24404143, 2014). "In addition, signaling pathways, such as the NF-κB, AMPK, and Akt/mTOR pathways, are considered important molecular targets for the alleviation of various liver diseases by betaine, and these results are consistent with the findings of our study." (PMID 39984861, 2025). "Targeted activation of EGFR and mTOR in BECs to convert this cell population to hepatocytes could represent a therapeutic avenue to treat these patients with advanced liver disease." (PMID 36625346, 2023). "We provide evidence that OTULIN is a crucial in vivo regulator of liver homoeostasis in mice and humans, identify mTOR signalling as a surprising driver of liver disease in OTULIN-deficient mice, and show that mTOR inhibition with rapamycin can improve liver pathology caused by OTULIN deficiency." (PMID 32231246, 2020). "More research is necessary to understand the mechanisms of how mTORC1 dysregulation provokes liver injury and pathologies, which could lead to the development of better mTOR-based therapeutics for various liver diseases." (PMID 32764389, 2020). "Overall, the identification of portal hypertension-induced mTOR signaling alterations may be highly significant due to its central roles in immune cell modulation, angiogenesis and hepatic fibrogenesis." (PMID 28535799, 2017). "An increasing number of evidences have indicated that human diseases have been closely correlated with TSC/mTOR pathway dysregulation, including many types of cancer, cardiovascular diseases, hepatic disease, immunological disorders, and neurological disorders." (PMID 28638431, 2017).